IL6 (interleukin 6)
Diseases named in the same sentence as IL6 in open-access papers (continued):
Sharing a sentence is not in itself a finding about the gene and the disease.
tumor (continued). "Interleukin-6 (IL-6) sustains a pro-tumor milieu by facilitating angiogenesis and tumor evasion of immune surveillance." (PMID 36497451, 2022). "IL-17 can promote the activation of the STAT3 signal transduction pathway through the intermediate mediator IL-6 in tumor cells." (PMID 36544490, 2022). "One such potential mechanism governing therapeutic resistance unveiled in the present study is the previously unrecognized role of neutrophil-derived IL-1β in driving iCAF polarization and CAF-tumor cell IL-6/STAT-3 signaling in the PDAC TME." (PMID 36107485, 2022). "The results indicate that parameters related to IL-6 have high a impact on cancer cell growth, such that decreasing the level of IL-6 can remarkably slow the tumor’s growth." (PMID 36294824, 2022). "AIF-1 was mainly expressed in the cytoplasm of macrophages infiltrating the tumor tissue and positively correlated with IL-6 and VEGF expression in both clinical NSCLC samples and TCGA NSCLC samples." (PMID 36520870, 2022). "IL-6 helps to create an inflammatory and immunosuppressive tumor microenvironment that promotes tumor angiogenesis and outgrowth." (PMID 36182930, 2022). "Its activity drives intestinal inflammation by inducing other proinflammatory cytokines, such as IL-6, IL-17, and IL-22, and therefore promotes tumor cell survival." (PMID 35884974, 2022). "Here, we first detected the NOX activity which was generally identified as a tumor-promoting factor at different time periods (4 h, 8 h, 12 h, 16 h, 20 h, and 24 h) in IL6-induced EC cells." (PMID 35692503, 2022). "IL-17 promotes tumorigenesis through the production of myeloid-derived suppressor cells (MDSCs) and stimulates IL-6 secretion from stromal tumor cells activating the STAT3 pathway." (PMID 35682971, 2022). "Further exploring the mechanism showed that GZMA enhanced the inflammatory response and mediated tumor progression by inducing the production of IL6 in macrophages and activating pSTAT3 pathway in cancer cells." (PMID 35464869, 2022). "M2 macrophages secrete some anti-inflammatory factors, such as IL-4, IL-6, and IL-10, which negatively regulate the immune response in tumours." (PMID 35923703, 2022). "As measured by liver appearance, we found that injection of either NVP-BEZ235 or anti-IL-6 Ab inhibited the tumour progression of HCC to a certain extent but was very limited." (PMID 35165269, 2022). "In fact, ablation of the NDL tumor combined with aPD-1 resulted in a 12-fold increase in Il6 gene expression." (PMID 36451859, 2022). "These secreted proteins promote the recruitment, generation, and expansion of Th17 cells, an independent lineage of Th cells that further promote tumor growth through the IL-17/IL-6/STAT3 functional axis." (PMID 35488263, 2022). "Tumor-derived IL-6 is reported to be involved in the induction of tolerogenic DC phenotypes, but can switch the monocyte differentiation to macrophages rather than DCs." (PMID 35784290, 2022). "The continuously activated JAK/STAT pathway in the tumour microenvironment can inhibit the antitumor immune response of immune cells, and IL-6/JAK/STAT signaling has become a popular signal target for tumour therapy." (PMID 36042480, 2022). "Both TNF and IL-6 represent so called “acute phase proteins” that stimulate the liver to produce and secrete other inflammatory ligands that trigger both general and tumor-type-specific carcinogenic effects." (PMID 35205678, 2022). "IL-6 plays an important role in tumor cell growth and survival, angiogenesis, immune regulation of the TME, stromal cell activation, and ultimately disease progression." (PMID 35223512, 2022). "Targeting the IL-6 receptor with Tocilizumab to block IL-6 effects on WM tumor cells was shown to reduce IgM levels and deter tumor growth in WM, while not inducing toxicity." (PMID 36232447, 2022). "Immune cells are the natural source of cytokines; nevertheless, tumor cells are able to produce IL-6 and TNFα as well." (PMID 35269507, 2022).
tumor (continued). "M2-type TAMs can produce tumor-promoting factors such as IL-6 and VEGF, MMP-2, MMP-7 to promote angiogenesis, thereby promoting tumorigenesis.The ratio of M1/M2 TAMs varies among individuals and in different immune microenvironments." (PMID 35965533, 2022). "In cancer, mifamurtide induces the activation of monocytes and macrophages against tumors via the secretion of IL-6, TNFα and increased anti-tumor activity of infiltrating immune cells." (PMID 35884563, 2022). "The removal of ICOS-Fc from IL MIX resulted in it having a lesser effect on tumor growth (mass, volume), cell proliferation (Ki67), and immune modulation, in terms of IL-1β, IL-6, and IL-10 expression." (PMID 36500861, 2022). "The use of the IL6R monoclonal antibody tocilizumab prevented BMI1 upregulation by blocking IL6 function, demonstrating a reduction in tumor growth in subcutaneous injected xenografts." (PMID 35159370, 2022). "Serum IL-6 and IL-8 were found to closely reflect tumor growth and killing, with observation of logarithmic increase in No T mice as tumor progressed." (PMID 36463361, 2022). "β-adrenergic activation also induces the expression of pro-inflammatory cytokines such as IL-6 and IL-8 in cancer and immune cells in the tumor microenvironment, which contributes to tumor growth." (PMID 36611747, 2022). "iCAFs lack increased αSMA expression and instead secrete interleukin-6 (IL-6) and are distant from tumor cells." (PMID 36225934, 2022). "In turn, enhanced osteoblast activity drives tumor progression by releasing interleukins 6 and 8 (IL-6 and IL-8) and insulin growth factor (IGF-1)." (PMID 36077840, 2022). "On the other hand, the release of IL-6 from skeletal myocytes in response to exercise indirectly inhibits neoplasm onset and development by increasing the mobilization and infiltration of cytotoxic immune cells, thus engaging muscle–immune cell crosstalk." (PMID 35454797, 2022). "For instance, the application of IL-6 antibody reduced the tumor size stimulated by 17β-estradiol and decreased the expression of phosphorylated (p)- Stat3 in nucleus of EC cells." (PMID 36531027, 2022). "IL-6, a multifunctional and pleiotropic cytokine, is secreted by various cells including tumor cells, monocytes, CAFs, adaptive immune cells and vascular endothelial cells." (PMID 36313280, 2022). "This is a new type of transient and regulated cancer immunoediting process that operates under the control of inflammatory cytokines (IL-6) orchestrating the induction of a reversible immune-excluded tumor microenvironment." (PMID 36443756, 2022). "Tumour cells-derived IL-6 production has the ability to disrupt the DC maturation, migration and differentiation." (PMID 35406451, 2022). "Concomitant events include the secretion of tumor-promoting pro-inflammatory cytokines (IL-6, TNFα and IL23) and the production of immune suppressive factors (e.g., Arg1, TGFβ, and IDO)." (PMID 35237269, 2022). "Skeletal muscle can secrete cytokines such as IL-6, IL-8, and IL-15 in an autocrine, paracrine, or endocrine manner, which promotes systemic inflammation and subsequently tumor growth." (PMID 35241010, 2022). "As CD8+ tumor-infiltrating lymphocytes (TILs) influence the effects of ICIs, we further explored the correlation between IL-6 and CD8+ TILs." (PMID 35550592, 2022). "Tumor-associated macrophages (TAM) and microglia present in the TME secrete significant quantities of IL-6, thereby causing the proliferation and metastasis of malignant cells." (PMID 35054779, 2022). "The induction of osteoblast senescence by p27Kip1 promotes metastatic seeding, tumor growth and osteoclastogenesis mediated by IL-6 synthesis in mice." (PMID 35884405, 2022). "It is likely, therefore, that the high LRG1 expression levels observed in tumour endothelium are also driven by IL-6 and result in the subsequent disruption of endothelial-mural cell associations and consequential abnormal vascularisation." (PMID 35318338, 2022).
tumor (continued). "Lactate mediates partial crosstalk between tumor cells and macrophages, and also promotes the secretion of IL-6 and upregulates the expression of HIF1α." (PMID 36686771, 2022). "Poor overall survival was noted in tumours with high cytokine concentration such as high IL-6 and TNF-α." (PMID 34951691, 2022). "In contrast, recurrent tumors contain many immunosuppressive tumor-associated macrophages (TAMs) and Treg cells and the cytokines VEGF, IL-1β, IL-6, IL-10, and TGF-β, which suppress CD8+ T cells." (PMID 36685898, 2022). "Meanwhile, cytokines such as IL-6 and IL-10 can further stimulate the secretion of IL-34 by tumor cells and immune cells and promote the expression of IL-34." (PMID 35936748, 2022). "As a potential tumor growth factor for different cancer types, the secretion of IL-6 was also evaluated." (PMID 36248865, 2022). "Firstly, we detected several inflammation factors, such as LPS, TNFα, IL-1β and IL-6, in the sera of WT and Hectd3−/− mice burdening primary tumor (0 h) or surgically removed primary tumor 6 h or 12 h later." (PMID 35918322, 2022). "High serum IL-6 level is an independent predictor of poor prognosis of GC and GC cells can secrete IL-6, promoting tumor growth, development and migration." (PMID 36591515, 2022). "Our study suggests that miR‐126 affects the function of macrophages, subsequently suppresses epithelial transformation and ultimately inhibits tumour development via CXCL12/IL‐6 signalling." (PMID 35363937, 2022). "Specifically, interleukin-6 is known to for its significant role in tumor proliferation, migration, induction of microsatellite instability, and angiogenesis." (PMID 35071777, 2022). "Proinflammatory cytokines IL-1 and IL-6 act as tumor growth factors by combining specific receptors on the cell surface to induce the proliferation or prolongation of tumor cells." (PMID 36417428, 2022). "Just as metastasis formation is a common process occurring in a variety of types of cancer, aberrant IL-6 signalling provides another unifying motif that supports tumour growth and metastasis." (PMID 36429126, 2022). "Pathologically, IL-6 is produced by tumour stromal cells, immune cells, trafficking to the cancerous lesion, or the cancer cells themselves." (PMID 36429126, 2022). "For example, bone marrow fat cells secrete significant and regulated levels of IL-6, which promotes metastasis of tumor cells through the JAK2/STAT3 signaling pathway." (PMID 35498437, 2022). "Among these 9 candidate targets, AGT, DRD2, IL-1B, and IL-6 were significantly increased in primary tumor compared with the normal tissues, while ALB, IL-10, and IGF1 were significantly decreased in COAD tissues." (PMID 35280511, 2022). "Interleukin-6 (IL-6), which plays a major role in cancer progression, inhibits apoptosis in tumor cells and promotes angiogenesis." (PMID 36558948, 2022). "In a second pattern, the HER2pos/pSTAT3pos/IL-6neg tumor cell clusters were adjacent to regions of stroma that were IL-6 positive." (PMID 35565421, 2022). "TNF-α, IL-6, and IL-10 were all significantly higher in the Chemotherapy group compared with Tumor group." (PMID 36428795, 2022). "It is known that in the tumor microenvironment, many known circulating factors including IL-6, IFN-γ, TGF-β, VEGF, G-CSF, GM-CSF, M-CSF, and SCF induce the recruitment, accumulation, and activation of MDSCs and modulate MDSCs to produce more of NO and ROS." (PMID 35720398, 2022). "IL-6/JAK2/STAT3 pathway is more active in CD44+CD24- BC cells than in other tumor types, and inhibition of JAK2 reduces their numbers and prevents xenograft growth." (PMID 36591515, 2022). "Further research on this topic has revealed that IL-6 activates the STAT3 signaling pathway of tumor cells and promotes the expression of VEGF, thereby inducing angiogenesis." (PMID 35734400, 2022). "Recently, several studies have reported that chrysin can enhance the anti-tumor response of CTLs by activating APCs or decreasing the levels of IL-1β and IL-6." (PMID 36615387, 2022).
tumor (continued). "Second, many cells within the tumor microenvironment (TME) serve as a source of immunosuppressive cytokines including interleukin-6 (IL-6) and transforming growth factor-β (TGF-β) that further inhibit antitumor immune responses via redundant mechanisms." (PMID 35197076, 2022). "In pancreatic cancer, the increased expression of miR-let-7i in TDEs affects the levels of myeloid inhibitory intracellular inflammatory cytokines (IL-6, IL-17, IL-1β) and transcription factors, downregulating the anti-tumor immune response." (PMID 35359390, 2022). "CRNDE downregulation reduces MM cells adhesiveness, IL-6 production by MSCs co-cultured with CRNDEΔ/Δ tumor cells and increases sensitivity to bortezomib." (PMID 35454868, 2022). "Among the oncology biomarkers explored in HPV-related cancers, IL-6 stands out as a predictor of tumor development and immunosuppression." (PMID 36405719, 2022). "In the course of tumor progression, inflammatory cytokines, including IL-6 and IL-17, facilitate the proliferation of tumor cells, and several cytokines can play an antagonizing role in the immune cells of anti-tumor responses." (PMID 36140220, 2022). "Some studies have found that the immune score of tumor tissue and serum IL-6, IL-11, or CD4 + /CD8 + T cells can also reflect the immune-inflammatory state, but the method is costly, inconvenient, and difficult to apply in clinical practice." (PMID 35866083, 2022). "IL-6, released in response to infection, trauma, and neoplasia, shows higher concentrations in various cancer types, and in particular in individuals who are carriers of both G alleles for its SNP rs1800795." (PMID 35335997, 2022). "In the later stages of tumor formation, however, the infiltrating inflammatory cells are transformed into various inhibitory inflammatory cells that secrete IL-8, IL-6, and TGF-β, which promote NEPC formation." (PMID 35938167, 2022). "Taken together, our study revealed a novel mechanism by which IL6 induced mitochondrial mtDNA leakage, which in turn affected tumor immune escape." (PMID 35692503, 2022). "IL-6 secreted by both tumor cells and stromal cells is involved in the induction of osteoblastogenesis and bone resorption, which are key processes in the formation of the premetastatic niche in bone." (PMID 36497411, 2022). "On the contrary there was an increase in the Th2 mediators IL-4, IL-6, IL-27, soluble chemokine ligands and pro-inflammatory mediators responsible for promoting pro-tumor immune cells; MCP-1, and IL-16." (PMID 35154142, 2022). "IL-6 can participate in the angiogenesis of tumor tissue, thus playing an important role in tumorigenesis and development." (PMID 36091401, 2022). "After that, interleukins (IL) -1β, IL-6, ROS and nitric oxide (NO) are released to promote tumor proliferation and at the same time induce the polarized Th1 response." (PMID 35736173, 2022). "Interleukin-1 (IL-1), IL-6, and IL-8 are involved in inflammatory processes, among which IL-1 and IL-6 play an important role in tumor cell growth and metastasis." (PMID 35645817, 2022). "Arg1+ macrophages from tumor bearing mice secreted more IL-6 than Arg1- macrophages, and were capable of inducing tumor cell migration in the presence of IL-9." (PMID 35778404, 2022). "IL6-depletion in FAK-wt cells resulted in a significant reduction in tumour growth when compared to either FAK-wt or FAK-wt shRNA CTL tumours." (PMID 36138073, 2022). "To gain a better understanding of the role of pro-inflammatory cytokines in PCa progression, we analyzed messenger RNA (mRNA) levels of IL-6 and TNFα from 49 somatic tumor tissue samples (see “Methods” section)." (PMID 36371231, 2022). "IL-17 can trigger the production of IL-6, which increases tumor cell migration and invasion, therefore contributing to tumor drug sensitivity and resistance to chemotherapy." (PMID 35681689, 2022).
tumor (continued). "The immunohistochemistry results in tumor samples of PAAD patients showed that IL-6 expression was significantly higher than that in the matching normal tissue." (PMID 35630552, 2022). "Implicated CAF-derived factors in tumour development include TGFβ, LIF, CXCL12, IL6, IGF1, and MAPK and STAT3 signalling pathways." (PMID 36358721, 2022). "MSCs promote tumor development by secreting cytokines and growth factors such as interleukin-6 (IL-6) and TGF-β and vascular endothelial growth factor (VEGF)." (PMID 35953863, 2022). "Increased concentrations of IL-6 in the peripheral blood of CRC patients turned out to be associated with an advanced tumor stage, the development of metastasis, tumor recurrence, and reduced survival." (PMID 36428508, 2022). "Curcumin inhibited tumor-derived IL-6 to inhibit dendritic cell STAT3 and restore dendritic cell-mediated stimulation of T cell immunity." (PMID 36700235, 2022). "In mixed bone marrow chimeric tumor-bearing mice, Arg1-expressing cells also co-expressed IL-6 and the Arg1+ IL-6+ donors were mainly derived from WT donors." (PMID 35778404, 2022). "In lung cancer, tumor-associate macrophage (TAM) containing iron has been demonstrated to increase ROS level and secrets proinflammatory cytokines (e.g., TNFα, IL-6) to kill tumor cells." (PMID 35401569, 2022). "Continuous activation of STAT3 in tumor-associated immune cells activates the expression of downstream genes VEGF, IL-10 and IL-6, and causes the proliferation of tumor-infiltrating hematopoietic stem cells, which ultimately leads to poor prognosis." (PMID 36561336, 2022). "Hepatic thrombopoietin synthesis that arises in response to tumour-derived IL-6 induces an increase in platelet counts, promoting tumour growth and producing a positive feedback loop." (PMID 36077635, 2022). "ZEB1-mediated immune responses also contribute to inflammation in the tumor micromilieu via its direct regulatory effect on the expression of IL-6." (PMID 36402997, 2022). "A study revealed that some inflammatory mediators secreted by M1 macrophages, namely, chemokine (C-C motif) ligand 5 and IL-6, were found to be tumour supportive, suggestive of a poor prognosis." (PMID 36353102, 2022). "GSEA analysis of our RNA-seq data from the PSaRC318 tumor at relapse demonstrated upregulation of multiple immunoregulatory pathways including TNFα/NFκB, inflammatory response, TGFβ, IL6, IL2, and IFNγ." (PMID 36187937, 2022). "C/EBP-homologous protein (CHOP), which is overexpressed in tumor cells, can regulate pro-inflammatory cytokines, such as IL-23, IL-1β, and IL-6, and modulate the activity and survival of tumor cells by inhibiting the immune response of T cells." (PMID 35327508, 2022). "IL-6 alters the cell cycle suppressing apoptosis, stimulates the adhesion of tumour cells to endothelial cells, and promotes the process of tissue invasion and metastasis, increasing the expression of MMPs." (PMID 36358859, 2022). "More specifically, they found that inhibition of IL-6 with an IL-6 silencing vector was able to increase the cell killing effect of radiation in vitro, and delayed tumor growth following radiation therapy in an animal model." (PMID 35992826, 2022). "One way to combat tumor plasticity while also limiting myeloid recruitment and M2 differentiation is using IL-6 inhibitors." (PMID 36031601, 2022). "Smoking (p=0.050) and reduced performance status (p=0.011) resulted in higher IL-6 levels, whereas tumor (p=0.427) and nodal stages (p=0.334), tumor localization (p=0.439), and HPV status (p=0.294) had no influence." (PMID 34773163, 2022). "Consistently, S1P–S1PR1 signaling in tumor cells or the tumor microenvironment induced persistent STAT3 activation and IL-6 production, leading to tumor growth and metastasis." (PMID 35565311, 2022). "In our model, obvious expression of mouse IL‐6 protein was observed in Schwann cells at proximal sites of N‐inv tumor." (PMID 35578571, 2022).